CD163 (CD163 molecule)
Diseases named in the same sentence as CD163 in open-access papers (continued):
Sharing a sentence is not in itself a finding about the gene and the disease.
tumor (continued). "More importantly, there was also a significant correlation between IL‐8 expression level and the number of tumor CD68 positive but not CD163 positive macrophages, and we also found that IL‐8 and CD68 were coexpressed in PDAC tissue." (PMID 30311406, 2018). "While PD-L1 expression was slightly but significantly increased within the tumor core, we noted that neoadjuvant (NA) chemotherapy did not impact NKp46, CD163 and Foxp3 infiltrate." (PMID 30454021, 2018). "Our study uncovered that CD11b+/CD163+ M2 TAMs promote GSC maintenance and GSC-driven tumour growth through the PTN–PRPTZ1 signalling, demonstrating that PTN is a critical molecular mediator bridging TAMs and GSCs in GBM tumour microenvironment." (PMID 28569747, 2017). "For instance, tumor and T-regulatory cell-derived IL-10 can skew macrophages toward an anti-inflammatory phenotype characterized by activation of STAT3 and increased expression of CD163, CCL18, and SOCS3." (PMID 28881599, 2017). "CD163+ cell densities in each tumor region (TC or IM) did not allow the stratification of patients into groups with statistically different DFS or OS." (PMID 28428887, 2017). "M2 type, expressing CD163 and MRC1, promoted tumor growth, invasion, angiogenesis, and metastasis." (PMID 28549420, 2017). "CD163 has been used as a marker to evaluate macrophage infiltration, and its ectodomain (also called soluble CD163, sCD163) can be cleaved by ADAM17 (ADAM metallopeptidase domain 17) gene, which is closely related with tumor metastasis." (PMID 29152078, 2017). "PD-L1 expression co-localized with CD68 and CD163, supporting the idea that in our cohort PD-L1 is not mainly expressed by tumor cells but by myeloid cells." (PMID 28344870, 2017). "In contrast, PTN expression and the infiltration of CD163+ M2 TAMs were markedly reduced in tumour areas lacking GSCs, suggesting a co-distribution among GSCs, M2 TAMs and PTN." (PMID 28569747, 2017). "Eight cycles of NAC, on the other hand, did not alter the level of infiltration by CD68+ and CD163+ TIMs in post-NAC tumour specimens when compared with pre-NAC specimens." (PMID 28913366, 2017). "In a recent study, localization of CD163+ cells in the tumor stroma, but not the tumor nest was shown to be of clinical relevance for patients with BCa." (PMID 28428887, 2017). "Data obtained showed a similar distribution in E-cadherin levels between the two series examined, and protein expression was not correlated to density of tumor-infiltrating CD163+ macrophage." (PMID 27462782, 2016). "Hence, LGSOC patients showing an attenuated M2-skewed phenotype (CD163+) compared to HGSOC, also expressed significantly lower MMP-9 expression in tumor samples." (PMID 27462782, 2016). "Further phenotypic characterization of stabilin-1 positive cells using monocyte/macrophage marker CD163 revealed that CD68+Stab-1+ TAM co-expressed CD163 in certain tumor areas whereas CD68−Stab-1+ cells were typically negative for CD163." (PMID 27105498, 2016). "Importantly, number of genes responsible tumor immune responses and desmoplastic reaction; Mst1r, TGFβr1, TGFβr2, VEGFa, CSF-1, SDF-2, CD44, IL-6ra, PD1, CD68, CD163, fibronection and MMPs were significantly reduced." (PMID 26429877, 2015). "Galectin-1 expressing cells were not abundant in the tumor epithelium, but when present the majority was CD163+." (PMID 26066796, 2015). "The cutoff point >25 % of tumor cells expressing CD163 in tumor samples is correlated to DSS and DRFS rates suggesting that CD163 might be useful as macrophage/cancer cell fusion marker in clinical context." (PMID 26585897, 2015). "Likewise, reduced M2 features (expression of CD163 and production of IL-10) were found after crosslinking CD16 on the surface of monocytes to cetuximab-coated tumor cells." (PMID 26579227, 2015).
tumor (continued). "Inhibitory effect of CD163 expression was not investigated in this tumor model, because no CD163+ cells were detected in the tumor tissues of either the vehicle or CA administration group (data not shown)." (PMID 24738052, 2014). "In the present study, Foxp3-positive cell infiltration in the tumor tissue did not correlate with the patients’ survival or with other immunological parameters such as serum IL-8, IL-8(T) and CD163(IF)." (PMID 25461761, 2014). "The importance of the CD163/CD68 and M1/M2 ratio is found in several other tumor types." (PMID 25192022, 2014). "The total number of macrophages in tumor tissue did not correlate with OS in both groups, however, the CD163/CD68 ratio correlates with OS in the total patient group." (PMID 25192022, 2014). "The Authors found that lymphatic vessel density in the invasive front was significantly higher for high CD163+/CD204+ tumor samples compared to low samples but not statistically significant difference was found between the high and low CD68+ infiltration." (PMID 23950747, 2013). "An isotype antibody used as a negative control showed no CD163 staining in normal or tumour tissues." (PMID 23339669, 2013). "CD163 has been identified, previously, in non-neoplastic monocytes/macrophages and neoplasms of monocyte/histiocyte derivation." (PMID 23339669, 2013). "The amount of CD163 stain increased with tumour grade; staining was found in tumour cells but not of epithelial origin." (PMID 23339669, 2013). "In conclusion, we demonstrate that CD163 staining is lower than CD68, with less non-specific staining of background inflammatory cells and Hodgkin cells, therefore is a better marker for tumor associated macrophages." (PMID 22289504, 2012). "The CD163+ M2 macrophages were mainly distributed throughout the tumoral stroma, but not the tumor nest, in grade I OSCC." (PMID 24213108, 2011). "Harvested grafts maintained characteristic features of the original tumors with respect to tumor morphology, CSF1 translocation status, CSF1, and macrophage CD163 expression, making this the first PVNS model of practical use for preclinical therapeutic investigation." (PMID 20981142, 2010). "When the M1 and M2 macrophages on the tumor sections (including the tumor islets and stroma) were counted under high-power fields, approximately 70% of macrophages were CD68+/CD163+ M2 macrophages and the remaining 30% of them were CD68+/HLA-DR+ M1 macrophages." (PMID 20338029, 2010). "In addition, CD163 was associated with hormone receptor-negative breast cancer, while CD86 correlated with higher tumor grade." (PMID 40510346, 2025). "Interestingly, NR3C1 was co-expressed with MRC1 and CD163 in M03 cells, suggesting that NR3C1 may play a role in inhibiting immune-mediated tumor cell killing." (PMID 40260248, 2025). "Although additional markers such as CD163 (M2 macrophages), CD3/CD8 (T lymphocytes), or α-SMA (stromal fibroblasts) could provide a more comprehensive characterization of the tumor microenvironment, the present study was designed as an exploratory analysis with a limited sample size." (PMID 41373493, 2025). "Predominantly displaying a pro-tumoral CD163+ M2 phenotype, TAMs in SG tumors uniquely promote tumor progression through proliferation, metastasis, angiogenesis, immune evasion, and recurrence, notably lacking typical phagocytic activity towards tumor cells." (PMID 41164198, 2025). "Confocal 3D imaging revealed high density of immunosuppressive M2-like TAMs (CD163+) within TRPC-enriched regions, with proximity and frequent cellcell contact between these TAMs and TRPC cells, suggesting a direct role in immune modulation and tumor progression." (PMID 40661379, 2025). "In particular, bioinformatics analysis of MC interaction with other cells of the FGF23-producing tumour microenvironment, within an integral range of intertarget distances from 0 to 20 μm, disclosed their most frequent co-localisation with CD14+, CD31+, αSMA+, and CD163+ cells." (PMID 40981193, 2025).
tumor (continued). "Interestingly, studies on mice have shown that CD163-positive TAMs only infiltrate the margins of tumor tissues, not the center." (PMID 40355384, 2025). "Although LMO7 did not promote an increase in the percentages of CD3+ T cells, CD3+ CD8+ T cells, CD163+ macrophages, GranzymeB+ cells, and CD3+ FOXP3+ T cells among all nucleated cells, it induced Treg and dysfunctional CD8+ T cells to be in closer proximity to tumor cells." (PMID 39143228, 2025). "Finally, we examined the spatial distribution of key tumor microenvironment markers such as CD8A, PD-L1, FOXP3, CD163, and VEGFA, further confirming that TMErisk genes aggregate in the tumor center and recruit immune cells, forming an immune hub (Figures 6G1, G2, G3, G4, G5)." (PMID 40104502, 2025). "However, there is still no consensus on the relationship between CD163+ cells with tumor progression." (PMID 39703508, 2024). "APOC1 is primarily expressed in tumor cells and macrophages and shows a positive correlation with the expression of genes such as CD68, CD86, CD163, CXCL17, CXCL8, and IL-10, suggesting that APOC1 may promote tumor progression by influencing macrophage polarization." (PMID 39877420, 2024). "Interestingly, we found that CD68 and CD163 did not differentiate the two subtypes, with a similar number of positive cells in both the tumor parenchyma and the surrounding nontumorous tissue." (PMID 38611048, 2024). "Tumor-supporting activity is related to facilitating tumor invasion, proliferation and migration (mediated by CD204, CD206, CXCL16, stabilin-1, and RAGE), M2-like TAM polarization (by CD36, LOX-1, CXCL16, CD163, and RAGE), and tumor angiogenesis (by CD68, Dectin-1, and RAGE)." (PMID 39516356, 2024). "M1 macrophages have anti-tumor activity and are characterized by the expression of CD68, 80, 86, and MHC-II, and M2 macrophages that promote tumor growth and are characterized by the expression of CD163, 204, 206, and secretion of immunosuppressive cytokines such as IL-10 and tumor growth factor-β." (PMID 39624236, 2024). "Furthermore, immunohistochemical analysis of GC and adjacent paracancer tissues showed that almost 30% of tumor tissues exhibited high expression of CD163, while none of the adjacent paracancer tissues showed a high H score." (PMID 38422751, 2024). "We observed a significant increase in the number of stromal CD163+ TAMs with higher tumor stages, regardless of whether TNM (q = 0.04, Benjamini–Hochberg corrected Fisher exact test) or FIGO classifications (q = 0.001) were used." (PMID 38407373, 2024). "Furthermore, we observed a negative correlation between the level of soluble NKG2D ligands and the infiltration of memory T cells, while a positive correlation was found with the infiltration of CD163+CD206+ macrophages, which are known to promote tumor growth." (PMID 38254761, 2024). "We show that expression of classical macrophage-related molecules such as CD14, CD163, CD68 and several molecules involved in the function, differentiation and recruitment of macrophages in VS tissue using RT-qPCR, many of which show a correlation to VS tumour volume." (PMID 38480935, 2024). "In addition to data at the transcriptional level, IHC staining confirmed a decrease in protein levels of CD163 and CD206 (representing tumor-infiltrating M2 macrophages) with increased level of FERMT2 proteins (CD163, R = 0.543, P < 0.001; CD206, R = 0.500, P = 0.001)." (PMID 38352691, 2024). "Additionally, the expression of M1 macrophage markers CD86 and CD80 in tumor tissues surpassed that in adjacent tissues, while the expression of M2 macrophage markers CD163, CD206, and Arg-1 in tumor tissues was also higher than in adjacent tissues (p<0.05, p<0.01)." (PMID 39531417, 2024). "Alternatively, CD163 as a marker of immunosuppressive myeloid cells in tumor may not be sensitive enough to detect the diverse myeloid populations in the brain and could be underestimating or reflecting only a small subset of myeloid cells." (PMID 39346903, 2024).
tumor (continued). "Immunohistochemical staining showed elevated expression of CD163 and Ki-67 in mice treated with QGP-1-H-exo, underscoring the contribution of hypoxic pNEN cell-derived exosomes to M2 macrophage polarization and the establishment of an immunosuppressive tumor microenvironment (TME)." (PMID 38904015, 2024). "Tumor cells in all PDAC were negative for CD163 expression (100%)." (PMID 39462379, 2024). "RT-qPCR results indicated a significant upregulation in the expression of M2 macrophage markers (MRC1, CD163) within HCC-conditioned TAMs, while the expression levels of M1 markers (CD86, iNOS) remained unchanged, suggesting a skew towards M2 polarization in the tumor microenvironment." (PMID 38938448, 2024). "After 4 days of co-culturing with T98G cells, monocytes displayed phenotypical characteristics of tumor associated myeloid cells characterized by a 50% reduction in MHC-II MFI levels and high upregulation of the CD163 and CD206 marker compared to monocytes cultured without T98G cells." (PMID 39065651, 2024). "Moreover, tumor cells exhibited less positive staining with CD68 and CD163." (PMID 38189834, 2024). "Second, the markers from IHC-stained WSIs were limited to CD8, CD163, and PD-L1, which may not represent the entire tumor immune micro-environment." (PMID 36707660, 2023). "M1 macrophages have antitumor surface properties and exhibit inhibitory effects on tumor progression, while M2-polarized macrophages promote tumor progression by secreting vascular endothelial growth factor (VEGF) and other proangiogenic factors, such as CD163." (PMID 37566748, 2023). "Interestingly, our histological analyses of PDAC tissues also revealed that PD-L1 expression was predominantly located in the TME at the tumor invasion fronts along with a high proportion of macrophages (CD68+ and CD163+ cells) supporting the view that the main source of PD-L1 are stromal cells." (PMID 37449210, 2023). "By isolating CD11b+CD14+CD163+ macrophages from normal, peritumor, and intratumor tissues and performing RNA sequencing, we found that macrophage TMEM176B expression levels were lower in normal tissue but higher in tumor tissue, inversely correlating with the expression of CD146." (PMID 37308559, 2023). "M2 macrophages express CD163 in their cytoplasm, whereas tumor cells do not." (PMID 35280439, 2022). "In addition, VSIR was found to widely express on cancer cells, fibroblasts, macrophages, and T cells in many tumor types based on the single-cell sequencing analysis and co-express with M2 macrophage markers CD68, CD163 based on the immunofluorescence staining." (PMID 35493077, 2022). "Nevertheless, no changes in the CD163 expression were detected after adding the tumor cells to the macrophages, regardless of whether those cells were previously irradiated or left untreated." (PMID 34665291, 2022). "However, CD163 negative and CD163 positive tumours had similar ascorbate content, indicating that the macrophage ascorbate content did not drive tissue ascorbate levels." (PMID 36050369, 2022). "CD163 gene expression did not correlate with age, gender, tumor location, or relapse variables." (PMID 35567733, 2022). "Whilst there is some evidence that M2 can have tumour inhibiting activity specifically in OS lung metastasis, it appears that more detailed evaluation of sub-populations such as CD68−/CD163+ at the single cell level may be a better biological endpoint if the study were to be repeated." (PMID 35672690, 2022). "CD163 positive tumours had a significantly lower 5-hmC percentage than CD163 negative tumours (Mann–Whitney p = 0.0007), which may suggest that tumour cells contribute to the 5-hmC signal rather than macrophages." (PMID 36050369, 2022).
tumor (continued). "Although no coimmunostaining was performed, the morphological observations based on CD163 immunostaining counterstained with hematoxylin showed that CD163 immunostained cells occupied tumor areas as densely grouped cells that did not leave any place for lymphocytes." (PMID 35885058, 2022). "In addition, the positive signals of CD4+ T cells, macrophages (CD68+) and M2 macrophages (CD163+) were located in the microenvironment of the tumor invasion front, while CD8+ T cells were distributed not only in the microenvironment of the tumor invasion front but also within the tumor glands." (PMID 33818637, 2021). "In conclusion, higher levels of different TIL subsets were associated with stromal features such as high macrophage counts (CD163+), presence of vascular invasion, absence of stromal elastosis, as well as increased tumor cell proliferation and interval detection mode." (PMID 34076969, 2021). "We found that tumours with G-CSFhigh and CAIX+ phenotypes independently displayed highly significant positive correlations with the presence of intratumoural lymphocytes expressing CD8, PD-1, FOXP3, TIM3, and LAG3, with carcinoma cells expressing PD-L1, and with CD163+ M2 macrophages." (PMID 33804486, 2021). "Moreover, although the opsonization of tumor cells with murlentamab did not modify the proportion of TAMs expressing CD163, it decreased the proportion of TAMs positive for CD36 and CD206." (PMID 33924378, 2021). "However, after adjusting for hrHPV status, myeloid marker densities in the IT Tumor compartment were no longer significantly associated with survival (CD14 p = 0.65, CD68 p = 0.96, CD163 p = 0.53)." (PMID 34194435, 2021). "However, the infiltration of CD3+ and CD8+ T cells or CD68+ and CD163+ macrophages was not correlated with patients’ clinical features, such as age, gender, and tumor localization." (PMID 33804155, 2021). "To study whether the association of chemotherapy with the prognosis was independent from the immune markers in the different nodal stage and tumor stage patient groups, we performed multivariate Cox’s regression analyses (adjusted for the immune markers CCL2, CD68, and CD163)." (PMID 33467469, 2021). "After prognostic analysis with PD-L1/B7-H4 combined with FOXP3/CD163, it was found that the double high group (high PD-L1 high CD163, high PD-L1 high FOXP3 and high B7-H4 high FOXP3) shortened overall survival time, confirming that the inhibitory tumor microenvironment led to poor prognosis." (PMID 34307135, 2021). "Besides these omental cell types, tumour‐associated macrophages (TAM) clearly are instrumental in metastasis, in particular the CD163+Tim4+ subset, which promotes the stemness, invasive properties and epithelial to mesenchymal transition (EMT) of tumour cells by paracrine mechanisms." (PMID 34841720, 2021). "This study showed that although tumor-associated CD66b(+) neutrophils and CD163(+) macrophages were correlated with adverse prognostic factors in NSCLC—such as a higher CRP, a higher white blood cell count, larger tumor size, and necrosis—no direct link to the patients’ outcome was observed." (PMID 34885082, 2021). "We further found that ITGA3 was negatively correlated with monocyte markers (CD86), TAM markers (CCL2 and IL10), and M2 macrophage markers (CD163 and MS4A4A), suggesting that ITGA3 could regulate the polarization of TAMs and promote tumor growth and metastasis." (PMID 34094951, 2021). "In addition to participating in tumor metabolism, as the IF results showed, MCT1 and CD163 were colocalized on macrophages, and MCT1 may participate in the lactate uptake into CD163+ macrophages in the high-lactate TME." (PMID 33178603, 2020). "Specific depletion of this subset of TAMs by the anti-CD163 lipid nanoparticles containing doxorubicin resulted in reduced tumor growth and increased infiltration of monocytes and immature TAMs that advance inflammatory responses and recruitment of CD4+ and CD8+ T cells promoting tumor regression." (PMID 32752088, 2020).